BRCA1 (BRCA1 DNA repair associated)
Diseases named in the same sentence as BRCA1 in open-access papers (continued):
Sharing a sentence is not in itself a finding about the gene and the disease.
ovarian carcinoma (continued). "The endangered nature of this species prevents its use as an ovarian cancer model, though immunotherapies that enhance survival of patients with BRCA1-associated cancers could later play a role in the conservation of this species." (PMID 30049987, 2018). "The aim of the study was to evaluate the rate of pathogenic mutations in the 26 breast and ovarian cancer susceptibility genes in patients who meet the criteria for BRCA1/2 testing and to compare the accuracy of different selection criteria for second-line testing in a founder population." (PMID 29928469, 2018). "Since the approval of the first poly (adenosine diphosphate [ADP]) ribose polymerase inhibitor (PARPi; olaparib [LynparzaTM]) for platinum-sensitive relapsed high grade ovarian cancer, with either germline or somatic BRCA1/2 deleterious variants, the strategies for BRCA1/2 are dynamically changing." (PMID 29731958, 2018). "Furthermore, resistance to taxane containing regimens have been documented in serous high-grade ovarian carcinomas displaying BRCA1/2 germline mutations." (PMID 29453630, 2018). "Pathogenic variants in BRCA1 confer susceptibility to breast and ovarian cancer." (PMID 29996917, 2018). "Inactivating mutations in exon 11 of BRCA1 account for ~30% of breast and ovarian cancers." (PMID 30463359, 2018). "With BRCA status providing prognostic information and helping to predict sensitivity to cytotoxic agents, ovarian cancer management now sees patients “being selected in clinical practice for biomarker-directed therapy, based on presence of a BRCA1 or BRCA2 mutation”." (PMID 29752676, 2018). "We systematically reviewed the literature and relevant data repositories to characterise the prevalence and spectrum of germline variants in breast and ovarian cancer susceptibility genes in the Indian population, including putative BRCA1 and BRCA2 founder mutations." (PMID 35693198, 2018). "The recent approval of inhibitors of poly (ADP-ribose) polymerase (iPARP) in the treatment of ovarian cancer in the presence of a BRCA1/2 mutation has sparked the analysis of women with such diagnosis, which can further benefit from the detection of carriers in the family." (PMID 30103829, 2018). "Polymorphisms of other BER components, notably the glycosidase OGG1, result in an increased risk of ovarian cancer, especially in women who are BRCA1 deficient, and are a common finding with up to 63% of women with ovarian cancer carrying these germline variants." (PMID 29925418, 2018). "While the general population lifetime risk of ovarian cancer is low at 1.4%, women at high-risk of developing the disease due to their inheritance of a germline BRCA1 and BRCA2 mutation have an average cumulative risk of between 40% to 75% and 11% to 34%, respectively." (PMID 29506471, 2018). "In addition, for patients affected by breast and/or ovarian cancer, knowledge about their BRCA1/2 mutation status is important because it determines the therapeutic response and choice of medication (e.g., PARP inhibitors)." (PMID 29580235, 2018). "In ovarian cancers, BRCA1/2-mutated tumors are associated with high tumor-infiltrating lymphocytes demonstrating improved prognosis, and in addition to elevated mutations would be anticipated to have more frequent micronuclei, leading to activation of the STING response." (PMID 30120226, 2018). "BRCA1/2 mutations are associated with BC and ovarian cancer OC susceptibility." (PMID 29361751, 2018). "Thus far, many studies on BRCA1 have been concerned with the risk of breast and ovarian cancer in BRCA1 mutation carriers." (PMID 29492227, 2018). "Germline BRCA1 mutations predispose women to breast and ovarian cancer." (PMID 30327455, 2018). "The PARPi, olaparib, has shown efficacy in both the relapsed setting, in women with BRCA1/2 mutations and ovarian cancer, and when used as maintenance therapy in women with sporadic high grade serous ovarian cancer, improving progression-free survival time, when compared to placebo." (PMID 29925418, 2018).
ovarian carcinoma (continued). "A BRCA1 causative founder variants were detected in 10 of the 158 (6.3%) ovarian cancer cases." (PMID 29492181, 2018). "In women with BRCA1/2 deficiency within their ovarian cancer tissue, inhibition of PARP imposes an intolerable burden of DNA damage repair deficiency and may induce cell death." (PMID 29464354, 2018). "With the success of PARP inhibitors for patients with BRCA1/2 mutation-positive ovarian cancers, the focus is now on identifying other molecular abnormalities that may confer “BRCAness” to tumors without apparent BRCA mutations." (PMID 30382883, 2018). "Notably, carriers of pathogenic BRCA1 or BRCA2 variants (path_BRCA1 or path_BRCA2) have an increased risk of developing BC (average lifetime risk of 35–85%) and ovarian cancer (average lifetime risk 11–39%)." (PMID 29371908, 2018). "We confirm in this study the accuracy and precision of NGS workflow for simultaneous detection of CNVs and point mutations of BRCA1/2 genes, suggesting the use of this technological advancement in the diagnostic-therapeutic and care assessment of hereditary breast and ovarian cancer." (PMID 30263092, 2018). "Mutations in BRCA1 are associated with an increased risk of breast and ovarian cancer." (PMID 29511213, 2018). "BRCA1/2 mutations are responsible for 5–8% of breast and 10–20% ovarian cancer morbidity." (PMID 30211169, 2018). "In ovarian cancer, FDA-approved poly ADP-ribose polymerase inhibitors, olaparib and rucaparib, have been used for the treatment of ovarian cancer in patients harboring the BRCA1, BRCA2, and other DNA repair gene mutations and were sensitive to platinum-based chemotherapies." (PMID 29503809, 2018). "Because BRCA1&2 gene mutation carriers have a high risk of developing early-onset breast and ovarian cancer during their lifetime, the aim of this study is to determine whether plasma telomeric cfDNA level is associated with the BRCA1&2 mutations." (PMID 29423116, 2018). "The sensitivity of gastric cancer cells to auranofin could be increased by the silencing of genes involved in autophagy, and BRCA1 deficiency has further been implicated to increase sensitivity of ovarian cancer cells to auranofin." (PMID 30248944, 2018). "Mutations of BRCA1 are known to predispose women to both breast and ovarian cancers." (PMID 30327455, 2018). "BRCA1/2 mutations and even all “BRCAness” of malignancy, at least ovarian cancer and ovarian-related cancers, probably not only correlate with high efficacy of poly(adenosine diphosphate-ribose) polymerase inhibitors but also lead to a high-potential cure by orally administered melphalan." (PMID 29729664, 2018). "Therefore, the objective of this study was to analyze the cost effectiveness of the program for diagnosing the germline mutation in the BRCA1/2 genes and of the preventative strategies offered to the relatives of patients who develop ovarian cancer." (PMID 30517521, 2018). "Lifetime risks of ovarian cancer were 54% for BRCA1 and 23% for BRCA2 mutation carriers." (PMID 30301218, 2018). "Interestingly, 40% of captive jaguars develop ovarian carcinoma with non-synonymous mutations in BRCA1." (PMID 30049987, 2018). "In Poland, the causative founder variants in the BRCA1 are responsible for a significant proportion of ovarian cancer cases, however, regional differences in the frequencies of various mutations may exist." (PMID 29492181, 2018). "Clinically significant BRCA1/2 mutations in breast and ovarian cancers." (PMID 29459887, 2018). "The program for diagnosing a germline mutation in the BRCA1/2 genes and for preventative strategies, aimed at family members of patients diagnosed with ovarian cancer, proved to be a cost-effective alternative, from the perspective of the National Health System." (PMID 30517521, 2018). "Pan-cancer analysis reveals a similar signature in BRCA1-mutated breast and ovarian cancers." (PMID 30531861, 2018).
ovarian carcinoma (continued). "One of the largest case control studies to assess this effect of oral contraceptives found a reduced risk of ovarian cancer in carriers of BRCA1 mutations (odds ratio 0.56 (95% CI 0.45–0.71); p < 0.0001) and carriers of BRCA2 mutations (0.39 (95% CI 0.23–0.66); p = 0.0004)." (PMID 29466291, 2018). "The variety of options now accessible for the patient and physician in making appropriate and timely decisions in hereditary breast and ovarian cancer has triggered a daily increase in the demand for mutation analysis of the BRCA1/2 genes on the other continents." (PMID 30263132, 2018). "Very briefly, maintenance approvals are focused on patients with response to platinum used for relapse, while treatment approvals are focused on pretreated patients with deleterious BRCA1/2 mutated epithelial ovarian cancer, both for platinum-resistant or sensitive relapses." (PMID 30347758, 2018). "Also, in BRCA1-deficient ovarian cancer cells, RAD51 paralogs XRCC2 and XRCC3 are capable of loading enough RAD51 onto stalled forks (in an ATR-dependent manner), thus providing proto-resistance to PARPi that can evolve to full resistance." (PMID 29355244, 2017). "This requires a larger series of patients that may further explain the lack of antitumor responses to PARP inhibitors in patients with advanced BRCA1/2 mutation ovarian cancer." (PMID 28454085, 2017). "Marked responses have been observed in ovarian cancers with BRCA1/2 mutation, even if up to 50% of HGSOC having HRD may also be better treated compared to cancers with HRD negative (HR proficient) genotypes." (PMID 29214031, 2017). "We have investigated the clinical significance of the BRCA1 variant p.His1673del in 14 families from the Emilia-Romagna region of Italy, including 20 breast and 23 ovarian cancer cases; four families displayed site-specific ovarian cancer." (PMID 28186987, 2017). "For women with ovarian cancer and a BRCA1/BRCA2 germline mutation who are interested in risk-reducing breast surgery, realistic information should be presented in an individualized way, in order to facilitate women making decisions about their own life and body." (PMID 28780755, 2017). "In summary, a study of the levels of microRNA expression may have clinical implications for the diagnosis, prognosis and treatment of breast and ovarian cancer associated with the BRCA1 mutation." (PMID 29021870, 2017). "Furthermore, we have used multiple in silico tools to explore the functional effect of the variant, and investigated the mechanisms of BRCA1 loss of heterozygosity (LOH) in ovarian carcinomas occurred in carriers." (PMID 28186987, 2017). "This article reviews reported relationships between various miRNAs, such as miRNA-9, miRNA-146a, miRNA-182 miRNA-218, miRNA-638 and the response to cytostatic drugs, mainly to platins and PARP1 inhbitors, for the treatment of breast and ovarian cancer associated with BRCA1 mutations." (PMID 29021870, 2017). "As such, synthetic lethality is ideally suited to exploit the truncal loss-of-function alterations leading to CIN, and is best exemplified by the synthetic lethal targeting of BRCA1/2-deficient ovarian cancers with the PARP inhibitor, Olaparib (detailed above)." (PMID 29104272, 2017). "Germline or somatic mutations in the BRCA1 or BRCA2 gene have prognostic value in ovarian cancer since ovarian cancer patients with BRCA1/2 mutations are reported to have a better response to platinum-based treatment and subsequently a longer survival duration than patients without such mutations." (PMID 29179445, 2017). "Our results indicated that this integrated miRNA-lncRNA signature may have important clinical implications for risk stratification of ovarian cancer patients with wild-type BRCA1/2." (PMID 28978132, 2017).
ovarian carcinoma (continued). "Since 17 samples of patients with wildtype OC and 26 samples of BRCA1 mutation carriers with OC came from one institution (tumorbank ovarian cancer (TOC) of the Charité, Medical University of Berlin), we performed a test for interaction in order to identify possible laboratory or sampling bias." (PMID 29244844, 2017). "During evaluation of a breast and ovarian cancer gene panel for peripheral blood and breast cancer tumour tissue, BAMClipper approach detected BRCA1 and BRCA2 mutations that could otherwise be missed in conventional approaches due to edge or dilution effect." (PMID 28484262, 2017). "We conducted an international multicenter retrospective study to investigate the association between baseline clinical characteristics of patients with advanced BRCA1/2 mutation ovarian cancers from eight different cancer centers and their antitumor response to olaparib." (PMID 28454085, 2017). "Hereditary breast and ovarian cancer is characterized by mutations in BRCA1 or BRCA2 genes and PCR‐based screening techniques, such as capillary sequencing and next‐generation sequencing (NGS), are considered gold standard methods for detection of pathogenic mutations in these genes." (PMID 28717669, 2017). "The strongest genetic risk factors for ovarian cancer are mutations in the BRCA1/2 genes." (PMID 29246147, 2017). "These associations provide strong support for the hypothesis of a polygenic component for breast and ovarian cancer risks, respectively, that is largely shared between the general population and BRCA1 and BRCA2 mutation carriers." (PMID 28376175, 2017). "Approximately 10–15% of ovarian cancer cases are believed to be due to a BRCA1/2 mutation, however ~50% of individuals with a pathogenic BRCA mutation may not report a strong family history of cancer." (PMID 29246147, 2017). "If the test is validated, it might be used to screen women who are at high risk for ovarian cancer because of mutations in the BRCA1 and BRCA2 genes." (PMID 29087294, 2017). "The ages at which women with BRCA1 mutations would reach a cumulative risk of ovarian cancer of 2.8% are 48 years for those at the 1st percentile of the PRS, and 46, 45, 44, and 43 years for those at the 5th, 10th, 20th, and 30th percentiles of the PRS, respectively." (PMID 28376175, 2017). "The antitumor efficacy of olaparib in recurrent ovarian cancer is currently being assessed in the randomized phase III SOLO-3 trial, which compares olaparib monotherapy to physician's choice single-agent chemotherapy in patients with advanced BRCA1/2 mutated ovarian cancer (NCT02282020)." (PMID 28454085, 2017). "Besides ovarian cancer, olaparib has also shown potential efficacy in other cancers involving both germline and somatic BRCA1/2 mutations, including that of prostate, breast, gastric and pancreatic cancer." (PMID 28829366, 2017). "Interestingly, the hazard ratio estimate for the association of the ovarian cancer PRS with ovarian cancer risk was statistically significantly higher for BRCA2 than for BRCA1 mutation carriers." (PMID 28376175, 2017). "It appears that when deciding upon the future use of HE4 determination in ovarian cancer screening, the low values measured in patients with germinal BRCA1 mutation should be taken into account, which obviously requires further research in a significantly larger population of females." (PMID 28182133, 2017). "BRCA1 is one of the most researched breast and ovarian cancer susceptibility gene that has been found to be associated with γ-tubulin of centrosome and thus may act as an essential component of spindle formation." (PMID 29137675, 2017). "Germline heterozygous mutations in either BRCA1 or BRCA2 were previously shown to increase the overall risk of breast and of ovarian cancer by 40%–65% and 15%–45%, respectively; therefore, genetic testing of BRCA1/2 is used to diagnose hereditary breast and ovarian cancer syndrome (HBOC)." (PMID 29383094, 2017).
ovarian carcinoma (continued). "Eight of the BRCA1/2 mutation carriers with ovarian cancer had a partial response." (PMID 29214031, 2017). "However, despite this, variable response rates to PARP inhibitors have been observed in patients with advanced germline BRCA1/2 mutation tumors, including those with ovarian cancer." (PMID 28454085, 2017). "PTPI may be a useful indicator for informing both timing and sequence of non-platinum containing treatment regimens during the treatment journey of patients with advanced BRCA1/2 mutation ovarian cancer." (PMID 28454085, 2017). "In this international multicenter retrospective study, we investigated the baseline clinical characteristics that may predict for antitumor responses to treatment with the PARP inhibitor olaparib in patients with advanced BRCA1/2 mutation ovarian cancer." (PMID 28454085, 2017). "We hypothesized that common genetic variants in genes involved in BER might modify a woman’s lifetime risk of developing breast and ovarian cancer if she is a BRCA1 or BRCA2 mutation carrier." (PMID 29383107, 2017). "BRCA1, which is mutated in 10% of ovarian cancers, is a transcriptional regulator of MAD2 and the aberrant activity of mutant BRCA1 in ovarian cancer may lead to altered transcriptional regulation of MAD2 expression." (PMID 29254238, 2017). "In the 179 probands analyzed, an expectable correlation was found between cancer type and gene mutation: we found most cases with ovary cancer diagnosis to have mutations in BRCA1, 12 cases (one novel) compared with probands with a mutation in BRCA2, 2 cases (one novel)." (PMID 28947987, 2017). "Using NGS (covering all of the BRCA1/2 exons as well as the exon-intron junctions) of FFPE specimens obtained from 99 Taiwanese patients with ovarian cancer, we analyzed 1) germline and somatic BRCA1/2 mutations and 2) the occurrence of biallelic BRCA1/2 inactivation." (PMID 27907908, 2016). "Germline and somatic BRCA1/2 mutations define a subset of patients with ovarian cancer who may benefit from treatment with poly (ADP-ribose) polymerase inhibitors." (PMID 27907908, 2016). "In addition to BRCA1/2, several other genes have been identified which predispose women to breast and/or ovarian cancer." (PMID 26843898, 2016). "In addition, 35.5% of the patients with and 13.5% of the patients without first and/or second-degree relatives with breast and/or ovarian cancer were BRCA1/2 mutations carriers." (PMID 27914478, 2016). "However, only 7–9% of sporadic ovarian cancers exhibit BRCA1 30 mutations leading to inactivation of BRCA1, while 4% exhibit BRCA2 mutations." (PMID 26800494, 2016). "The same author analyzed 1171 unmatched ovarian cancer cases and investigated the presence of selected BRCA1 and BRCA2 mutations and, on the basis of his data, showed that the relative risk of developing stomach cancer in BRCA1 mutation carriers was 4.8 (95 % CI 1.5–15)." (PMID 26779294, 2016). "Our results found the total rate of BRCA1 mutations was 13.6 % in 125 ovarian cancer patients." (PMID 26753012, 2016). "Nonetheless, even if blood FEAT increases in non-cancerous diseases, serial measurements of blood FEAT might be useful for the follow-up of high-risk individuals such as patients with BRCA1/2 mutations for development of breast and ovarian cancers." (PMID 27659353, 2016). "In addition, although loss of heterozygosity was discovered in 41 ovarian cancer cell lines generally used in most laboratories, it was rare to find a complete loss of function caused by both of BRCA1 and BRCA2 mutations." (PMID 27385216, 2016). "Indeed, germline and somatic mutations in HR genes occur in about 30% of patients with ovarian carcinoma, of which up to 75% are in BRCA1 and BRCA2 genes." (PMID 26745875, 2016).